Y_RNA (Y RNA )
Gene: Miscellaneous RNA gene on chromosome 7 (115,207,894 to 115,207,996, reverse strand). Ensembl gene ENSG00000199764.
Homologues: Orthologues: chimpanzee Y_RNA (99% identical), macaque Y_RNA (92% identical), tropical clawed frog Y_RNA (73% identical). Paralogues in human: Y_RNA (86% identical), RNY3 (85% identical), Y_RNA (85% identical), Y_RNA (84% identical), Y_RNA (83% identical), RNY3P1 (83% identical), RNY3P16 (82% identical), Y_RNA (82% identical), RNY3P5 (81% identical), Y_RNA (81% identical), RNY3P13 (80% identical), RNY3P14 (80% identical), and 92 more.